FABP3 (fatty acid binding protein 3)
Diseases named in the same sentence as FABP3 in open-access papers (continued):
Sharing a sentence is not in itself a finding about the gene and the disease.
breast carcinoma (20 papers, 2008 to 2026). "In the tumor-adipose microenvironment (TAME) of breast cancer, the expression of FABP3 in lipid-associated macrophages (LAMs) is elevated." (PMID 40717587, 2025). "For example, breast cancer-associated fibroblasts (CAFs) promote lipid take up in tumor cells through the FABP2/FABP3 pathway, and ovarian cancer cells uptake fatty acids released by adipocytes through FABP4 to support metastasis." (PMID 40717587, 2025). "Studies have shown that breast cancer-associated fibroblasts (CAFs) promote lipid uptake in tumor cells through the FABP2/FABP3 pathway, thereby affecting tumor metabolism and growth." (PMID 40717587, 2025). "Only FABP2 and FABP3 mRNAs were found in the breast cancer cells; FABP2 expression was found to be modulated by hormones and after exposure to media conditioned by fibroblasts with increased lipid levels." (PMID 37207357, 2023). "FABP3 protein is a candidate for tumor suppressor of human breast cancer with a suggested role in arresting growth of mammary epithelial cells." (PMID 30009039, 2018). "In breast cancer and embryonic cancer cells, FABP3 acts as a tumor suppressor: FABP3 inactivation inhibits apoptosis and promotes proliferation; while FABP3 acts as an oncogene in gastric carcinoma, brain tumor and small cell lung cancer." (PMID 27323829, 2016). "More recent studies demonstrated the interaction between FABP3 and cancer biology in various types of cancer, including breast cancer, gastric carcinoma, brain tumor, and small cell lung cancer." (PMID 27323829, 2016). "In breast cancer immunotherapy models, inhibiting FABP3-enriched LAMs enhances the efficacy of anti-PD-1 therapy, suggesting that FABP3 may serve as a co-target for immunotherapy." (PMID 40717587, 2025). "Moreover, as found for FABP2, FABP3 mRNA was discovered in breast cancer culture cells where its expression is modulated by hormones and after exposure to media conditioned by fibroblasts." (PMID 37207357, 2023). "However, FABP3 has been reported to act as a tumor suppressor in breast cancer, and its transfection into breast cancer exhibited an antiproliferative effect." (PMID 36478991, 2022). "It is suggested that elevated expression of TPT1, PLIN2 and FABP3 might play a role in suppressing goat mammary tumor formation." (PMID 30009039, 2018). "FABP3 has been proposed as tumor suppressor in breast cancer." (PMID 18535662, 2008). "Additionally, FABP3 may influence breast cancer progression through lipid metabolism and immune regulation." (PMID 40717587, 2025). "Lipid metabolism and cancer cell adaptation: Research in breast cancer has found that FABP3 expression is negatively correlated with lipid transport protein FATP1, suggesting that FABP3 may play a regulatory role in metabolic adaptation between cancer cells and stromal cells." (PMID 40717587, 2025). "The proteins determined by SDS–PAGE to be expressed in mammary tissues in the rat model of DMBA-induced mammary cancer were thought to be HER-2, Nischarin, COX-2, Albumine, Vimentin, Actin, TNF-α, p16, and FABP3." (PMID 39070120, 2023). "Next, we determined the correlation between increased CD36 expression and the various FABP genes (FABP1, FABP2, FABP3, FABP4, FABP5 and FABP6) in the TCGA breast cancer cohort." (PMID 34561446, 2021). "FABP3, along with FABP4, is also the major component of the mammary-derived growth inhibitor (MDGI) which leads to the assumption that FABP3 inhibits the growth of human breast cancer cells." (PMID 38777142, 2024).
coronary artery disease (20 papers, 2012 to 2026). "Moreover, FABP3 has been defined as an independent predictor of CV events, including CV death, in subjects with suspected ACS, patients with HF and preserved ejection Fraction (HFpEF) and in subjects with stable coronary artery disease and impaired glucose metabolism." (PMID 36978893, 2023).
metabolic syndrome (20 papers, 2004 to 2025). A cluster of metabolic risk factors for CARDIOVASCULAR DISEASES and TYPE 2 DIABETES MELLITUS. "The methylation of FABP3 is associated with insulin, lipids, and cardiovascular phenotypes of the metabolic syndrome." (PMID 41019337, 2025). "FABP3's function is also associated with inflammatory conditions, insulin sensitivity, and metabolic syndrome." (PMID 38440405, 2024). "Taken together, these observations suggest that alterations in methylation of the FABP3 promoter region can be plausibly linked to various biological precursors of metabolic syndrome." (PMID 23510163, 2013). "In summary, the current study provides evidence that the methylation status of FABP3 is associated with phenotypes of metabolic syndrome." (PMID 23510163, 2013). "Furthermore, FABP3 methylation was associated with lipid, insulin, and blood pressure indicators, affecting metabolic syndromes in humans." (PMID 40239869, 2025). "FABP3 inhibition, hence, may be a useful pharmaceutical approach in obesity, metabolic syndrome, and type 2 diabetes." (PMID 38960943, 2024). "Dyslipidemia is independently associated with AF incidence, and lipid metabolism related proteins serve as a potential AF biomarker (such as LDL, VLDL, HDL, and FABP3)." (PMID 34899326, 2021). "In addition, the CpG methylation of FABP3 strongly affects metabolic syndrome and can lead to obesity." (PMID 32138348, 2020). "In addition, increased serum levels of FABP3 have been reported in patients with metabolic syndrome and non-alcoholic fatty liver disease, suggesting that FABP3 may serve as a biomarker of insulin resistance and subclinical myocardial damage." (PMID 37255976, 2023). "This study demonstrated that (a) PPARγ agonists improved insulin sensitivity and ameliorated dyslipidemia in HF fed rats and ZDF rats, which were correlated with serum adiponectin; (b) Serum adiponectin was positively correlated with adipose FABP3 mRNA in GI262570-treated rats." (PMID 15491498, 2004).
Obesity (19 papers, 2012 to 2025). Accumulation of substantial excess body fat. "Overexpression of FABP3 has been linked to obesity, type 2 diabetes, and cardiovascular diseases." (PMID 38440405, 2024). "A study revealed the relationship between FABP3 and obesity in vivo and the effects of FABP3 on signal transduction for glucose uptake in skeletal muscle cells in vitro." (PMID 38704563, 2024). "The level of FABP3 protein in gastrocnemius muscles increased significantly with an increase in body weight and metabolic phenotypes in obese mice, suggesting a close relationship between FABP3 expression in the muscle and the development of obesity and/or insulin resistance in mice." (PMID 38704563, 2024). "Our proteomics pathway analyses highlighted other proteins involved in lipoprotein metabolism (APOA1, BMP1, FABP3 and ANGPTL4) and that are key markers in obesity and NAFLD56–58." (PMID 32514005, 2020). "Heart-type fatty acid binding protein (H-FABP or FABP3) is involved in lipid metabolism and was predicted to relate to renal lesions in obesity." (PMID 23029183, 2012). "In addition, proteomic pathway analyses highlighted other proteins involved in lipoprotein metabolism (APOA1, BMP1, FABP3 and ANGPTL4) that are key markers in obesity and NAFLD." (PMID 36678141, 2023). "Besides, the transcription of other transportation-related genes, FABP3 and FABP-pm, was decreased in the atria of obesity and restored after LCA supplementation." (PMID 34899326, 2021). "Our work revealed the critical role of MUSTN1 in regulating adipogenesis by interacting with FABP3 and activating the PI3K/AKT signaling pathway, providing a theoretical foundation and a potential molecular target for improving animal performance and treating obesity-related diseases." (PMID 40239869, 2025). "Notably, in men with obesity and DM2, the genes up-regulated due to bright light include fibroblast growth factor 1 (FGF1), vasorin (VASN), ribonuclease A family member 1 (RNASE1), pappalysin 1 (PAPPA), Interleukin 7 (IL7), and fatty acid binding protein 3 (FABP3)." (PMID 40981208, 2025).
Alzheimer disease (17 papers, 2012 to 2025). A progressive, neurodegenerative disease characterized by loss of function and death of nerve cells in several areas of the brain leading to loss of cognitive function such as memory and language. "It has also been reported that FABP3 has been implicated in several diseases, including cardiovascular diseases, diabetic nephropathy, cancer, and Alzheimer’s disease." (PMID 40428342, 2025). "Furthermore, the increased presence of FABP3 in the plasma of Parkinson’s disease patients indicated its potential benefit in predicting disease risk and discriminating from other α-synucleinopathies and Alzheimer’s disease, using multi-marker analyses." (PMID 38069360, 2023). "In addition, FABP3 has potential as biomarker for disease monitoring: epidemiological studies have shown a close association between elevated levels of FABP3 in sera of patients with Parkinson’s and Alzheimer’s disease and disease progression." (PMID 32856199, 2020). "Here, we histologically studied FABP3 expression in human tissues obtained from patients with synucleinopathies, patients with Alzheimer disease (AD) and controls." (PMID 33841128, 2021). "Three papers describing FABP3 levels in serum, but only one was related to Alzheimer’s disease and the other two of them to dementia with Lewy bodies (DLB) and proteomic studies performed on MCI Down Syndrome (DS) and also on AD-DS patients." (PMID 34300173, 2021). "Higher FABP3 levels have been observed in the cerebrospinal fluid and serum of patients with Alzheimer’s disease, dementia with Lewy bodies or Parkinson’s disease." (PMID 34068550, 2021). "Here, we pathologically studied FABP3 expression in human tissues obtained from patients with synucleinopathies, patients with Alzheimer disease (AD) and controls (CNs)." (PMID 33841128, 2021). "Elevated CSF FABP3 levels have been reported in other neurodegenerative disorders including, Alzheimer disease, and Creutzfeldt-Jakob disease." (PMID 23144710, 2012). "Notably, higher FABP3 levels are observed in patients with dementia with Lewy bodies than in Parkinson’s disease dementia and Alzheimer’s disease, indicating the potential of FABP3 as a biomarker distinctive to dementia with Lewy bodies." (PMID 38069360, 2023). "FABP3 seems to be lipid metabolism-related biomarker in Alzheimer's disease." (PMID 35223953, 2022). "The genes, which play a vital role in the TUBB3 (formation of beta-tubulin), FABP3 (regulates alpha-Synuclein uptake in dopaminergic neurons) and CALM1 (Calcium signal transduction pathway) in Alzheimer’s disease, were upregulated." (PMID 40520681, 2025). "FABP3, the major neuronal FABP in the adult brain, is upregulated in the CSF of patients with Alzheimer’s disease (AD)." (PMID 39561115, 2024). "In addition, patients with DLB and PD show higher FABP3 levels in the serum than those with Alzheimer’s disease and non-demented subjects." (PMID 32210174, 2020).
dementia (16 papers, 2017 to 2025). Loss of intellectual abilities interfering with an individual's social and occupational functions. "Increased NfL levels were most strongly associated with the dementia stage of AD, but increased Fabp3 levels were more sensitive to milder AD stages and correlated with both CSF tau markers." (PMID 30253800, 2018). "In a recent study, Bäckström and colleagues found that high levels of FABP3 and neurofilament light chain protein, together with low Aβ1–42, were significantly associated with the development of dementia after 5–9 years of follow-up in a large cohort of patients with PD." (PMID 28750675, 2017). "In support of this notion, elevated levels of NF-L and FABP3 in CSF have been shown to be predictive of future dementia in PD patients." (PMID 40161513, 2025). "These investigations spotlight the pathogenic significance of the cerebrospinal fluid and serum FABP3 levels, indicating characteristic modifications in Parkinson’s disease, Parkinson’s disease dementia, and dementia with Lewy bodies." (PMID 38069360, 2023). "Serum FABP3 levels are increased in patients with Parkinson’s disease and dementia with Lewy bodies compared to healthy controls." (PMID 38069360, 2023). "This confirms FABP3 as a sensitive biomarker of pre-dementia neurodegeneration as previously reported." (PMID 37454217, 2023). "Additionally, an α-synuclein mimicking peptide that inhibits the binding and aggregate formation of α-synuclein-FABP3 is capable of restoring memory and learning abilities in a Parkinson’s disease dementia mouse model." (PMID 38069360, 2023). "Overall, the present study indicates that FABP3 mediates αSyn neurotoxicity in septal GABAergic neurons and the resultant cognitive impairment, and that FABP3 in this subpopulation could be a therapeutic target for dementia in synucleinopathies." (PMID 33401521, 2021). "Taken together, FABP3 could be a molecular target for both Parkinsonism and dementia in synucleinopathies." (PMID 33401521, 2021). "However, some findings may endorse specific roles of FABP3 in AD dementia development, because elevated CSF FABP3 levels have been shown to correlate with atrophy of the entorhinal cortex and amyloid pathology in AD-vulnerable brain regions." (PMID 28750675, 2017). "Of note, the CSF levels of FABP3, MDH1, and GDI1 were not only significantly elevated in participants diagnosed with AD, but also in the non-dementia classed MCI group when compared to CNC." (PMID 37775827, 2023). "On the contrary, AA is a ligand of the fatty acid-binding protein 3 (FABP3), which has been described as an early biomarker of dementia and PD and highly expressed in dopaminergic neurons." (PMID 33803760, 2021). "However, while UCHL1 and FABP3 appeared to be specific for AD, PKM activity increased in both AD and FTD patients, underlining that these two diseases may share alterations of energy metabolism that should be further explored as candidate pathways involved in dementia." (PMID 37454217, 2023). "Patients with PD without dementia had levels of FABP3 similar to those of the OND group and were characterized only by reduced t-tau CSF levels." (PMID 28750675, 2017). "Increased FABP3 levels were found in the CSF of patients with different neurological disorders, including Creutzfeldt-Jakob disease (CJD), AD in both its prodromal and dementia phases, and vascular dementia (VAD)." (PMID 28750675, 2017). "In addition, serum FABP3 was elevated in dementia with Lewy bodies and Parkinson’s disease with dementia, compared to non-dementia controls." (PMID 38069360, 2023). "However, previous studies found elevated peripheral FABP-3 levels in dementia with Lewy bodies, but not AD." (PMID 36631909, 2023).
dementia (continued). "Furthermore, in subsequent studies using patient blood, we revealed that plasma NF-L and FABP3, along with other plasma neurodegenerative-related proteins, such as UCH-L1 and t-tau, would be useful for the differential diagnosis of LB diseases, including PD and dementia with LB (DLB)." (PMID 40161513, 2025).
synucleinopathies (16 papers, 2019 to 2025). "In summary, these results suggest that FABP3 is specifically associated with αSyn aggregates in individuals with synucleinopathies." (PMID 33841128, 2021). "FABP3 deficiency also prevents the spreading of α-synucleinopathy-like pathologies following the injection of α-synuclein preformed fibril (PFF) in the mouse brain and uptake into dopaminergic neurons." (PMID 32752296, 2020). "Although FABP3 has been suggested to promote αSyn aggregation in animal models and to potentially be a useful biomarker for synucleinopathies, it remains to be elucidated whether FABP3 accumulation is associated with αSyn aggregation in human tissues." (PMID 33841128, 2021). "Using primary cultured neurons from FABP3 KO mice, it was further demonstrated that FABP3 is critical for αSyn uptake into dopaminergic neurons via caveolae-mediated endocytosis coupled with dopamine D2L receptors, suggesting a novel pathogenic mechanism for synucleinopathies." (PMID 37207357, 2023). "Our findings suggest that the αSyn decoy peptide represents a novel therapeutic approach for reducing the accumulation of toxic αSyn‐FABP3 oligomers in the brain, thereby preventing the progression of synucleinopathies." (PMID 36786129, 2023). "Altogether, FABP3 appears to be involved in αSyn uptake into dopaminergic neurons and to enhance the propagation of αSyn aggregates, suggesting FABP3 as a potential therapeutic target for synucleinopathies." (PMID 37207357, 2023). "FABP3 co‐localization with αSyn aggregates has also been observed in the brains of patients with synucleinopathies." (PMID 36786129, 2023). "Highlights of our results include detection and characterization of a binding relationship between αSyn and FABP3 that results in production of toxic oligomeric species that are relevant to the progression of synucleinopathies." (PMID 33862084, 2021). "Overall, there reports suggest that LC-PUFA-bound FABP3 makes complexes with αSyn and thereafter promotes its oligomerization and aggregation under pathological conditions such as oxidative stress in synucleinopathies." (PMID 33401521, 2021). "Taken together, the FABP3 inhibitor MF1 has the ability to prevent synucleinopathy-like behavioral deficits following mouse α-Syn PFF, and also human α-Syn PFF, injection." (PMID 32210174, 2020). "FABP3 is critical for α-synuclein uptake in dopaminergic neurons, preventing the development of synucleinopathies, such as Parkinson’s disease." (PMID 32856199, 2020). "This would be a situation encouraging animal research on the use of FABP3 in positive chaperonotherapy, by administering the chaperone to test its efficacy in controlling the progression of synucleinopathies and similar protein-aggregation pathologies." (PMID 32856199, 2020). "Recently, we developed the fatty acid-binding protein 3 (FABP3) ligand MF1 (4-(2-(1-(2-chlorophenyl)-5-phenyl-1H-pyrazol-3-yl)phenoxy) butanoic acid) as a therapeutic candidate for α-synucleinopathies." (PMID 32752296, 2020). "Our findings suggest that FABP3 is a novel molecular target for the development of α-synucleinopathy therapeutics and that an FABP inhibitor such as MF1 is an attractive candidate to treat patients with PD and/or DLB." (PMID 32210174, 2020). "Our data suggest that FABP3 contributes to the vulnerability of dopaminergic neurons during neuronal degeneration in Parkinson’s disease and other synucleinopathies." (PMID 31661838, 2019). "Published data indicate that FABP3 is critical for preventing synucleinopathies; therefore, its downregulation in cells harboring the m.13513G>A variant could lead to impaired alpha-synuclein uptake and formation of aggregates." (PMID 36975485, 2023). "In the present study, we demonstrated, for the first time, that FABP3 is associated with αSyn aggregates in autopsied brain tissues of patients with synucleinopathies but not with amyloid β or p-tau aggregates." (PMID 33841128, 2021).